ZEB1 (zinc finger E-box binding homeobox 1)
Diseases named in the same sentence as ZEB1 in open-access papers (continued):
Sharing a sentence is not in itself a finding about the gene and the disease.
lung carcinoma (continued). "E2F1, NR4A2, and ZEB1 reappear coexpressed in the LCII network, further verifying their importance for the establishment and progression of lung cancer since they are also in the LC&LD network and in the LCI network." (PMID 36101460, 2022). "SARS-CoV-2 infection in lung cancer cell lines reduces ACE2 expression and upregulates Zinc Finger E-Box Binding Homeobox 1 (ZEB1)." (PMID 33391502, 2021). "EMT marker analysis revealed that ZEB1 expression was increased, and Claudin-1 expression was decreased in CD44-overexpressing lung cancer cells." (PMID 34439211, 2021). "CD44 overexpression significantly increased migration and invasion abilities of lung cancer cells through CD44-induced ERK phosphorylation, ZEB1 upregulation, and Claudin-1 downregulation." (PMID 34439211, 2021). "Upregulation of c-Myc molecule in turn promoted the expression of ZEB1, ZEB2, and SNAIL gene, which ultimately enhanced epithelial to mesenchymal transition (EMT) and lung cancer metastasis." (PMID 34168109, 2021). "Meanwhile, EMT in lung cancer cells was meditated by the close interaction between ERK and ZEB1 pathway." (PMID 31952541, 2020). "Profiling the epithelial‐mesenchymal transition‐related molecular markers demonstrated decreased CDH1, TJP1, and OCLN and increased ZEB1, FN1, and EZH2 in response to CDKN2A silencing in lung cancer cells." (PMID 33155773, 2020). "miR-101 inhibits lung cancer proliferation and metastasis by targeting ZEB1, and miR-200c is an EMT-inhibitory miRNA that also targets ZEB1." (PMID 32674274, 2020). "Several EMT-TFs such as Slug, Twist, ZEB1, and FOXC2 had higher immunoreactivity in brain metastasis than lung cancer." (PMID 33291558, 2020). "The mRNA and protein expression of EMT markers Vimentin, Zeb1, Snail, and Slug were markedly increased in PC9 lung cancer cells co-cultured with MSCs compared to PC9 cells cultured in the absence of MSCs." (PMID 33119681, 2020). "Overexpression of PHRF1 was able to induce ZEB1’s expression, whereas suppression of PHRF1 impeded ZEB1 and EMT in lung cancer cells, most likely by a compelling involvement of PHRF1 in collaboration with Rpb1." (PMID 32730336, 2020). "In lung cancer cells, TDRG1 enhances the migration, metastasis, and malignancy of cancer cells by promoting ZEB1 expression through miR-873-5p down-regulation." (PMID 32664703, 2020). "ZEB1 up-regulates ITGA1 to recruit miR-181b, thus relieving ADCY9 to drive metastasis in lung cancer cells." (PMID 30813457, 2019). "TBK1, a downstream effector of the miR-200c-driven pathway, facilitates EMT and invasiveness of lung cancer cells by controlling synthase kinase-3β (GSK-3β) phosphorylation and zinc finger E-box-binding homeobox 1 (ZEB1) expression." (PMID 31817646, 2019). "MiR-205 depletion releases the ZEB1 and SRC suppression (as both are miR-205 targets) and induces EGFR tyrosine kinase inhibitor resistance in EGFR mutant lung cancer." (PMID 30813457, 2019). "In the mouse lung cancer model, RAS induces the expression of ZEB1 inducing cancer-initiating cells which are necessary for EMT and metastasis." (PMID 30065348, 2018). "ZEB1 is correlated with lymphatic and distal metastasis and influences metastasis via EMT in lung cancer." (PMID 29426364, 2018). "Among them, CTNNB1, ZEB1, CDC42, HSP90AA1, BST2, PCNA, and E2F1 have all been shown to promote lung cancer progression, while SAMHD1, HRAS, and NQO1 serve as tumor suppressor genes." (PMID 28498804, 2017). "Our results suggest that TLE1 induces anoikis insensitivity in lung cancer cells by repressing E-cadherin expression, at least in part, via the EMT transcription factor ZEB1." (PMID 29069783, 2017). "ZEB1 is one of the well-known transcription factors on EMT and metastasis, emerging resistance to therapy and poor prognosis in breast, pancreatic, and lung cancer." (PMID 27793006, 2016).
lung carcinoma (continued). "Through the regulation of ZEB (zinc finger E-box-binding homeobox) transcription factors (ZEB1 and ZEB2), E-cadherin (CDH1), vimentin (VIM), the down-regulated miR-200 family promotes EMT in the progression of lung cancer." (PMID 27005669, 2016). "We report here that metastasis suppressor p66Shc expression is dependent on cell density in lung cancer cells and represses the oncogenic EMT-activator ZEB1." (PMID 25837484, 2015). "In lung cancers, H3K27 acetylation level was higher in the tumor compartment than in the corresponding stroma where ZEB1 was more often expressed." (PMID 24216980, 2013). "Furthermore, ZEB1 facilitates alternative splicing and isoform expression of CD44, an HA receptor, and CD44 knockdown suppresses the motility and invasiveness of lung cancer cells." (PMID 40178908, 2025). "Treatment of lung cancer cells with HA heightened their mobility and invasiveness by inducing partial EMT, particularly evident in mesenchymal-like (high-ZEB1) 344SQ and H1299 cells compared with epithelial-like (low-ZEB1) 393P and HCC827 cells." (PMID 40178908, 2025). "Also, LDHA knockdown in lung cancer cells resulted in MET induction through decreased E-cadherin and increased vimentin, N-cadherin, Snail, and ZEB1 expression." (PMID 40507273, 2025). "In conclusion, our study first demonstrated that FOSL1/CIB2/ZEB1 pathway functioned in regulation of gefitinib resistance and CIB2 could be applied as a novel biomarker for diagnosis of drug resistance of lung cancer." (PMID 39264588, 2024). "Additionally, USP51 can interact with ZEB1, and the reduction of USP51 levels increases ZEB1 ubiquitination, significantly lowering cisplatin resistance in lung cancer cells." (PMID 38702734, 2024). "In lung cancer, STK11 knockdown has been reported to increase cell motility and invasiveness and influence many epithelial–mesenchymal transition (EMT) pathway marker proteins, such as ZEB1 and E-cadherin." (PMID 38461159, 2024). "Indeed, miR-182 and miR-183 mimics decreased PI4K2A levels in H1299 and CALU-1 mesenchymal lung cancer cells and in HCC827_ZEB1, an epithelial LUAD cell line that has acquired mesenchymal properties owing to ectopic ZEB1 expression." (PMID 36757799, 2023). "Studies on the extracellular effect of LOXL2 have revealed that the MiR200/Zinc finger E-box-binding homeobox 1(ZEB1) induces LOXL2-mediated collagen stabilization and deposition in TME, which can activate the ITG-β1/FAK/Src pathway in lung cancer cells and promote tumor invasion and metastasis." (PMID 36293126, 2022). "Moreover, HORMAD1-mediated regulation of EMT-related markers was eliminated by ZEB-1 knockdown, suggesting that ZEB1 is required for HORMAD1-induced EMT process in lung cancer cells." (PMID 35347116, 2022). "For example, while miR-218 suppresses protein levels by targeting SLUG and ZEB2 in lung cancer, it does not have such an effect on ZEB1." (PMID 35201505, 2022). "MTHFD2 was involved in lung cancer cell proliferation, migration, and apoptosis by mediating its downstream molecules, such as DNA helicases (MCM4 and MCM7), as well as ZEB1, Vimentin and SNAI1, which contributed to tumor cell growth and epithelial-to-mesenchymal transition (EMT) process." (PMID 35790743, 2022). "Given the possible link between RBM24 and ZEB1 in gastric cancer, it will be also of interest to examine whether and how RBM24 modulates ZEB1 expression and EMT in lung cancer." (PMID 35406615, 2022). "Finally, to confirm the in vitro and in vivo findings, we analyzed the expression of ZEB1, BMI1, and ALDH1A1 by immunohistochemistry in lung cancer specimens obtained from 20 NSCLC patients before treatment and after relapse during treatment with gefitinib." (PMID 33764690, 2021). "Indeed, ZEB1 and ZEB2 exhibited positive correlation with GSDME transcript across 188 CCLE lung cancer cell lines." (PMID 34901025, 2021).
lung carcinoma (continued). "Nobiletin, the main ingredient of citrus peel, has been found to attenuate the H1299 (human lung carcinoma cell line) cells' invasion and migration and downregulate the expression of EMT-related transcription factors Twist, Snail, and ZEB1/2, thereby inhibiting the EMT process of lung cancer cells." (PMID 32377312, 2020). "The overexpression of ZEB1 decreased the promoter activity of the AGR2 gene, which resulted in reduced AGR2 protein level and the acquisition of a more invasive phenotype of these lung cancer cells." (PMID 32570918, 2020). "Additionally, Western blot indicated that miR-374a and miR-374b enhanced ZEB1 and vimentin protein levels, indicating that miR-374a and miR-374b partially induced EMT in lung cancer cells." (PMID 32674274, 2020). "Therefore, we selected lung cancer cell lines A549 and H1299 differing in AGR2 expression to study in more detail the crosstalk between ZEB1 and AGR2 proteins." (PMID 32570918, 2020). "Indeed, the correlation between EMT, increased ZEB1/2-dependent expression of MDR1 and ABCG2, and resistance to platinum-based drugs was confirmed by the whole transcriptome profiling of ovarian and lung cancer tissues." (PMID 32266287, 2020). "Additionally, ZEB1 and ZEB2 overexpression have been found in several human cancers, including non–small cell lung cancer (NSCLC)." (PMID 32730336, 2020). "For example, it has been reported that NEAT1 can promote lung cancer progression through the miR-377-3p–E2F3 axis, regulate EMT through the miR-204/ZEB1 pathway in nasopharyngeal carcinoma, and serves as a downstream target of ERα to play a critical role in carcinogenesis of prostate cancer." (PMID 29515109, 2018). "In lung cancer, tumor buds display decreased levels of membranous β-catenin, while in CRC and oral squamous cell carcinomas they display reduced levels of miR-200 family which are strong inhibitors of ZEB1/2." (PMID 27136592, 2016). "We also demonstrated that ZEB1 upregulation was observed in additional NSCLC cell lines and human samples with EMT-related EGFR-TKI resistance, suggesting that ZEB1 is a possible target to overcome this kind of resistance in clinical lung cancer." (PMID 26789630, 2016). "Indeed, overexpression of claudin-1 was shown to induce EMT through activation of slug and zeb1 in human liver cells, and to mediate TNF-alpha induced cell migration in human lung carcinoma." (PMID 25171249, 2014). "Furthermore, Vcl knockdown in 344SQ lung cancer cells selectively decreased Snai1 expression without affecting Zeb1, another mesenchymal marker." (PMID 40563579, 2025). "However, additional transcription factors may be involved including HMGA2, ZEB1 and TWIST2, known to be involved in lung cancer." (PMID 41184222, 2025). "Taken together, we confirm that EMT transcription factor ZEB1 plays a major role in the invasion and metastasis of lung cancer and that FBXO11 can ubiquitinate ZEB1 and be recognized by the proteasome for degradation, thereby inhibiting the invasion and metastasis of lung cancer cells." (PMID 39409891, 2024). "Here, we show that miR-34a regulates PI4KB activity through this mechanism and that ZEB1 silences miR-34a and miR-182/-183 to coordinately inactivate PI4KB and increase PI4K2A levels, thereby executing a PI4KB-to-PI4K2A dependency switch that drives lung cancer progression." (PMID 36757799, 2023). "Moreover, an upregulation of APC and β-catenin was shown to significantly increase the levels of matrix MMP-9 and MMP-2 (members of the metalloproteinase family) expression and downregulate E-cadherin, Snail1, and Zeb1 expression, which ultimately resulted in EMT and bone metastasis in lung cancer." (PMID 34568020, 2021).
lung carcinoma (continued). "Moreover, lung cancer buds do not express ZEB1 (the predicted master regulator of EMT) at a significantly upregulated level as compared to the main tumor mass." (PMID 27136592, 2016). "Our results showed that ZEB1 promoted NOTCH1 but not Jagged1 in lung cancer cells, suggesting that the ZEB1/miR-200 axis may regulate NOTCH signalling through differential mechanisms in different types of human cancer cells." (PMID 27456471, 2016). "The data presented here, indicated that knockdown of topoisomerase IIα and overexpression of JWA suppressed lung cancer cell migration and invasion abilities, which might be partially ascribed to elevated E-cadherin expression and decreased MMP-2/9, N- cadherin, ZEB1, slug and snail levels." (PMID 26046674, 2015). "To determine whether a correlation exists in human tumors between ZEB1 expression and H3K27 acetylation, we examined corresponding immunohistochemical stainings on a commercial tissue microarray containing a series of human lung cancers." (PMID 24216980, 2013). "Moreover, while ZEB1 was found increased, SLUG mRNA levels were significantly decreased in Skip N2 samples, suggesting a possible molecular action of these genes may play role during the pathogenesis of Skip N2 metastasis of lung cancer." (PMID 35201505, 2022). "ZEB1 induces the promotion of EMT and in combination with other factors triggers metastasis and is highly expressed in aggressive cancer cell lines and the overexpression of the protein may be an indicator of poor prognosis in breast, pancreatic, and lung cancer." (PMID 29337896, 2018). "Notably, most of these studies address the role of ZEB1 by using cells or mouse models that express mutant KRAS, without exploring whether ZEB1 has different roles in lung cancer cells without KRAS mutations." (PMID 27456471, 2016). "Moreover, this miRNA was also found able to reduce the GSK3β expression, always in lung cancer stem cells, as well as of activating the Wnt signaling pathway in gastric cancer cells through the induction of epithelial-mesenchymal transition (EMT) and the expression of VIM, SNAI1 and ZEB1." (PMID 27275761, 2016). "Notably, epithelial–mesenchymal transition (EMT) transcription factors such as ZEB1, Slug, and TWIST1 have been identified as drivers of EGFR TKI resistance mediated by EMT, suggesting that these transcription factors could be potential targets for treating EMT-related resistance in lung cancer." (PMID 40304000, 2025). "In this study, mRNA levels of EMT-related genes ECAD, VIM, ZEB1, SLUG was evaluated in Skip N2 metastasis, which is a common entity in the lymphatic spread of the tumor in lung cancer patients and the molecular mechanism has not yet been elucidated." (PMID 35201505, 2022). "However, to the best of our knowledge, no study has examined the expression of both ZEB1 and BMI1 in lung cancer specimens from patients with acquired resistance to EGFR‐TKI." (PMID 33764690, 2021). "Moreover, genome-wide transcript analysis of tumor samples confirmed a close correlation between ZEB1 and HAS2 (but not with HAS1 and HAS3) in breast, pancreas and lung cancer specimens (GSE42568, GSE28735 and GSE41271)." (PMID 28086235, 2017).
colorectal cancer (193 papers, 2009 to 2026). A primary or metastatic malignant neoplasm that affects the colon or rectum. "ZEB1 overexpression has been linked to tumor progression and metastasis in various cancers, including breast and colorectal cancer." (PMID 40278350, 2025). "In colorectal cancer cells, ER stress has been directly linked to the induction of ZEB1 (zinc finger E-box binding homeobox 1)." (PMID 40278350, 2025). "The EMT-transcription factor ZEB1 is heterogeneously expressed in tumor cells and in cancer-associated fibroblasts (CAFs) in colorectal cancer (CRC)." (PMID 38937629, 2024). "Next, we performed immunohistochemical (IHC) staining on genome-sequenced primary human colorectal cancers tissues to evaluate the correlation between the expression of ZEB1, CDH1 and TRPS1 mutation." (PMID 39307879, 2024). "NEAT1 exhibited upregulation in both colorectal cancer tissues and cells, and knockdown of NEAT1 inhibited colorectal cancer proliferation and causes decreased ZEB1 expression and increased miR-448 expression." (PMID 39830506, 2024). "Collectively, these results demonstrate that the TRPS1 mutation significantly promotes colorectal cancer metastasis by activating ZEB1 expression, thereby enhancing epithelial to mesenchymal transition." (PMID 39307879, 2024). "Increased expression of ZEB1 was associated with worse survival in several types of digestive cancers, e.g., pancreatic, gastric and colorectal cancers." (PMID 34198662, 2021). "Similar functions have been seen in colorectal cancer where ZEB1 promotes a metastatic shift and loss of cellular polarity by repressing the expression of the polarity factor Lgl212." (PMID 32309604, 2018). "Aberrant expression of ZEB-1 in endometrial cancers, colorectal carcinomas and prostate cancer has been associated with aggressive disease, poor differentiation, the development of metastases and poor clinical prognosis." (PMID 24304617, 2013). "Interestingly, ZEB1 was shown to be induced in chronically inflamed intestinal mucosa and to promote intestinal inflammation and colitis-associated colorectal cancers through the repression of the N-methyl-purine glycosylase MPG-encoding gene." (PMID 36765930, 2023). "Glutamine deficiency might reduce E-cadherin in colorectal cancer through increasing zeb1 and zeb2, further studies are needed to confirm this finding." (PMID 35869517, 2022). "Earlier studies revealed that the positive expression of ZEB1 in endometrial cancers, colorectal carcinomas, and hepatocellular and prostate cancer was associated with aggressive disease, poor differentiation, the development of metastases, and a poor clinical prognosis." (PMID 29245917, 2017). "Higher expression of ZEB1 associated with higher aggressive capacity, poor differentiation, development of metastases, and poor clinical prognosis had recently been revealed in endometrial cancers, colorectal carcinomas, and prostate cancer." (PMID 25544793, 2014). "ZEB1 ablation in fibroblasts of mice bearing colorectal cancer impaired the barrier function of CAFs by decreasing collagen deposition." (PMID 41244268, 2025). "In colorectal cancer, miR-873-5p prevents metastasis of cancer cells by targeting ZEB1, which is involved in epithelial-mesenchymal transition." (PMID 40442738, 2025). "Knockdown of ZEB1 inhibited the F. nucleatum-mediated promotion of proliferation, migration and invasion in colorectal cancer cells." (PMID 39757156, 2025). "Recently, it has been reported that over-expression of GLUT3 up-regulated EMT-related genes such as N-cadherin, Vimentin, and ZEB1 down-regulated the expression of E-cadherin in colorectal cancer." (PMID 38594707, 2024). "Fibroblast-specific Zeb1 knock-out in colorectal cancer models leads to a shift in myCAF and iCAF populations, promoting immune infiltration." (PMID 38937629, 2024).